RGS10 (regulator of G protein signaling 10)
Description:
Regulates G protein-coupled receptor signaling cascades, including signaling downstream of the muscarinic acetylcholine receptor CHRM2. Inhibits signal transduction by increasing the GTPase activity of G protein alpha subunits, thereby driving them into their inactive GDP-bound form. Modulates the activity of potassium channels that are activated in response to CHRM2 signaling. Activity on GNAZ is inhibited by palmitoylation of the G protein.
Tractability: Small molecule: a structure with a bound ligand is known. Antibody: its Gene Ontology location is reachable by antibodies, with high confidence. PROTAC: ubiquitination databases record sites on it; its protein half-life has been measured.
Gene: Protein-coding gene on chromosome 10 (119,499,817 to 119,543,294, reverse strand). Ensembl gene ENSG00000148908.
Subcellular location: Cytoplasm, cytosol (Isoform 1); Nucleus
Subcellular location (Human Protein Atlas): Nucleoplasm; Nuclear bodies
Pathways (Reactome):
Signal Transduction: G alpha (i) signalling events
Gene Ontology:
Molecular function: G-protein alpha-subunit binding; GTPase activator activity; protein binding; GTPase activity
Biological process: G protein-coupled acetylcholine receptor signaling pathway; positive regulation of GTPase activity; G protein-coupled receptor signaling pathway; regulation of G protein-coupled receptor signaling pathway
Cellular component: cytosol; nuclear body; nucleoplasm; nucleus; plasma membrane; synapse
Genetic constraint (gnomAD): Loss-of-function variants: 6 observed, 16.48 expected, observed/expected ratio (o/e) 0.36, 90% interval 0.2 to 0.72. The upper end of that interval is the gene's LOEUF score, 0.72, which puts it in group 2 of 6, group 1 being the genes least tolerant of losing a copy. Missense variants: 149 observed, 192.13 expected, observed/expected ratio (o/e) 0.78, 90% interval 0.68 to 0.89. Synonymous variants: 69 observed, 74.51 expected, observed/expected ratio (o/e) 0.93, 90% interval 0.76 to 1.13.
Homologues: Orthologues: chimpanzee RGS10 (99% identical), dog RGS10 (96% identical), pig RGS10 (96% identical), macaque RGS10 (92% identical), mouse Rgs10 (92% identical), guinea pig RGS10 (89% identical), rabbit RGS10 (88% identical), rat Rgs10 (88% identical), tropical clawed frog rgs10 (69% identical), Drosophila melanogaster loco (44% identical). Paralogues in human: RGS12 (44% identical), RGS14 (41% identical), RGS3 (33% identical), RGS1 (31% identical), RGS4 (30% identical), RGS18 (29% identical), RGS21 (28% identical), RGS9 (28% identical), RGS8 (27% identical), RGS19 (27% identical), RGS20 (27% identical), RGS5 (27% identical), and 11 more.
Diseases named in the same sentence as RGS10 in open-access papers:
RGS10 is named in the same sentence as 53 diseases in open-access papers, as found by Europe PMC text mining. Sharing a sentence is not in itself a finding about the gene and the disease. The quoted sentences say what the papers report.
ovarian carcinoma (11 papers, 2010 to 2025). A malignant neoplasm originating from the surface ovarian epithelium. "We recently linked the suppression of RGS10 expression to ovarian cancer cell survival and chemoresistance, and further showed RGS10 knock down to increase cell growth and survival." (PMID 24475290, 2014). "We identify two important epigenetic regulators, HDAC1 and DNMT1, which are highly associated with the RGS10 promoter in chemoresistant ovarian cancer cells." (PMID 24475290, 2014). "Together these data suggest the loss of acetylation at RGS10 promoters contributes to the loss of RGS10 expression in two independent cell models of chemoresistant ovarian cancer." (PMID 24475290, 2014). "We identify two important epigenetic regulators, HDAC1 and DNMT1, that exhibit aberrant association with RGS10 promoters in chemoresistant ovarian cancer cells." (PMID 24475290, 2014). "To establish a renewable, homogeneous cell model of the loss of RGS10 expression in ovarian cancer, we compared RGS10 expression in IOSE cells and the serous epithelial ovarian cancer cell line CAOV-3." (PMID 23533674, 2013). "Loss of RGS10 in these cells contributes to multiple phenotypes, such as overactive microglia-mediated neuroinflammation and subsequent neurodegeneration, cardiac hypertrophy, and ovarian cancer chemoresistance, respectively." (PMID 34912341, 2021). "Our results suggest that epigenetic histone modifications may contribute to the loss of RGS10 expression in ovarian cancer cells, and that DNA methylation may contribute to further loss of expression during acquired chemoresistance." (PMID 23533674, 2013). "Similarly, cellular deficiency in RGS10 promotes chemoresistance in ovarian cancer." (PMID 37649067, 2023). "However, other Gi-coupled GPCRs are implicated in ovarian cancer proliferation and survival signaling, such as endothelin, chemokine, and prostaglandin receptors, suggesting RGS10 and RGS17 may regulate multiple survival pathways besides LPA." (PMID 21044322, 2010). "In microglia and ovarian cancer cells, RGS10 regulates inflammatory signaling by a G protein-independent mechanism, linking RGS10 to the inflammatory signaling mediators tumor necrosis factor-alpha (TNFα) and cyclooxygenase-2." (PMID 39145770, 2024). "In ovarian cancer cells, inhibition of RGS10 expression promotes the activation of the AKT signalling pathway, leading to enhanced cell proliferation, which in turn promotes the progression of ovarian cancer." (PMID 37924113, 2023). "RGS10 is an important regulator of cell survival and chemoresistance, and RGS10 transcript expression is significantly suppressed in multiple ovarian cancer cell lines." (PMID 24475290, 2014). "We investigate here the molecular mechanisms of epigenetic regulation of RGS10 expression in ovarian cancer cells and focus on chemosensitive parental A2780 cells and their derivative cell line, chemoresistant A2780-AD." (PMID 24475290, 2014). "Here, we fully investigate the molecular mechanisms of epigenetic silencing of RGS10 expression in chemoresistant A2780-AD ovarian cancer cells." (PMID 24475290, 2014). "We next sought to determine if pharmacologic inhibitors of histone deacetylation and DNA methylation can alter the expression of RGS10 in chemoresistant ovarian cancer cells." (PMID 24475290, 2014). "Together these data indicate that accumulation of DNMT1 at the RGS10 promoter likely contributes to suppression of RGS10 during ovarian cancer chemoresistance." (PMID 24475290, 2014). "In this manner, DNMT1 and HDAC1 synergistically contribute suppression of RGS10 transcription expression as ovarian cancer progresses." (PMID 24475290, 2014). "In our current study, we demonstrate specific contribution of two important epigenetic regulators, HDAC1 and DNMT1, to the suppression of RGS10 expression in chemoresistant ovarian cancer cells." (PMID 24475290, 2014).
ovarian carcinoma (continued). "Together, these data indicate that HDAC1 accumulation at RGS10 promoters likely contributes to suppression of RGS10 in chemoresistant ovarian cancer cells." (PMID 24475290, 2014). "Together these data suggest that HDAC1 mediated reduction of RGS10 expression blunts the ability of cisplatin to induce cell death in A2780/AD ovarian cancer cells." (PMID 24475290, 2014). "We recently showed that RGS10 transcript expression is suppressed during acquired chemoresistance in ovarian cancer." (PMID 24475290, 2014). "Our results further imply that the increased expression of DNMT1 and HDAC1 results in the generation of repressive complexes which target RGS10 promoters and cooperate in regulating ovarian cancer progression." (PMID 24475290, 2014). "In contrast to total protein abundance, ChIP assays reveal that binding of DNMT1 is significantly increased at the RGS10 promoter in chemoresistant cells as compared to chemosensitive ovarian cancer cells." (PMID 24475290, 2014). "We have previously reported that expression of RGS10, which normally suppresses growth and survival signaling pathways triggered by G-protein coupled receptors, is suppressed as ovarian cancer cells develop chemoresistance." (PMID 23533674, 2013). "Taken together, RGS10 transcript and protein expression is reduced in primary ovarian cancer cells and the CAOV-3 cancer cell line relative to immortalized ovarian epithelial cells, and in A2780 cells relative to parental cells." (PMID 23533674, 2013). "Here we report RGS10 suppression in primary ovarian cancer and CAOV-3 ovarian cancer cells compared to immortalized ovarian surface epithelial (IOSE) cells, and in A2780-AD chemoresistant cells compared to parental A2780 cells." (PMID 23533674, 2013). "In the current study, we investigated the epigenetic regulation of RGS10 expression in ovarian cancer cells." (PMID 23533674, 2013). "RGS10 protein expression was markedly lower in cells from each patient, suggesting that RGS10 expression is suppressed in clinical ovarian cancer." (PMID 23533674, 2013). "RGS10 regulates ovarian cancer cell growth and survival, and RGS10 expression is suppressed in cell models of ovarian cancer chemoresistance." (PMID 23533674, 2013). "To determine if RGS10 is also downregulated in primary ovarian cancer cells, we immunoblotted lysates from the benign, immortalized IOSE cell and from six primary epithelial ovarian cancer cell samples isolated from patient ascites." (PMID 23533674, 2013). "Our previous data demonstrated downregulation of RGS10 transcripts in ovarian cancer cell lines with acquired chemoresistance." (PMID 23533674, 2013). "First, we compared IOSE immortalized ovarian surface epithelial cells versus CAOV-3 ovarian cancer cells, as these cells displayed the greatest fold difference in RGS10 expression." (PMID 23533674, 2013). "We focus on two models of RGS10 suppression – CAOV-3 ovarian cancer cells compared to benign ovarian epithelial cells, and chemoresistant A2780-AD cells and their chemosensitive parental cells." (PMID 23533674, 2013). "Our previous observation that RGS10 is suppressed in chemoresistant cells was made in published transcript expression datasets from chemosensitive and chemoresistant ovarian cancer cell pairs." (PMID 23533674, 2013). "RGS10 transcript expression is downregulated in multiple models of acquired chemoresistance in ovarian cancer, and RGS10 expression levels alter ovarian cancer cell sensitivity to cisplatin and taxane cytotoxicity." (PMID 23533674, 2013). "An obvious candidate survival pathway is the PI3K/AKT pathway, which is activated in ovarian cancer cells via Gi G-proteins, targets of deactivation by RGS10 and RGS17." (PMID 21044322, 2010). "Indeed, in ovarian cancer cells, the GTPase RGS10 accelerated the hydrolysis of GTP bound to RHEB, thereby inactivating RHEB and mTORC1 activity." (PMID 39762645, 2025).
ovarian carcinoma (continued). "RGS10 may represent a biomarker of clinical staging for ovarian cancer and is one of five signature genes involved in the occurrence and development of ovarian cancer." (PMID 39145770, 2024). "Moreover, RGS2 and RGS10 are found to inhibit cell proliferation in ovarian cancer, whereas RGS19 gives rise to the opposite effect on ovarian cancer progression." (PMID 37118788, 2023). "RGS10 transcript and proteins levels are suppressed in several cells, including macrophages, microglia, neurons, cardiomyocytes, and ovarian cancer cells." (PMID 34912341, 2021). "Indeed, in ovarian cancer cells, histone de-acetylation at the RGS10-1 promoter correlates with suppression of RGS10 and chemoresistance." (PMID 24782983, 2014). "Hence, we focused here on therapeutic approaches to decrease chemoresistance by enhancing RGS10 expression in chemoresistant ovarian cancer cells." (PMID 24475290, 2014). "RGS10 is an important regulator of cell survival and chemoresistance in ovarian cancer." (PMID 24475290, 2014). "Thus, we determined the effects of a combination of TSA and 5-Aza-dC treatments on RGS10 expression and cell viability in chemoresistant ovarian cancer cells." (PMID 24475290, 2014). "Loss of RGS10 is not a universal feature of ovarian cancer cells; for example, while RGS10 expression is dramatically suppressed in CAOV-3 cells, it is not significantly suppressed in SKOV-3 serous epithelial ovarian cancer cells (not shown)." (PMID 23533674, 2013). "Taken together, our data suggest that chemotherapy exposure triggers loss of RGS10 and RGS17 expression in ovarian cancer cells, and that loss of expression contributes to the development of chemoresistance, possibly through amplification of endogenous AKT signals." (PMID 21044322, 2010). "In addition to the methylation regulation, other epigenetic modifications have also been clarified later in ovarian cancer cells, such as the HDAC-induced histone deacetylation, which participates in regulating the expression of RGS10 in the ovarian cancer cells with chemoresistance." (PMID 37118788, 2023). "However, the mechanisms governing RGS10 expression in ovarian cancer are poorly understood." (PMID 23533674, 2013). "Changes in RGS10 expression in ovarian cancer have not been reported, but interestingly it has recently been shown that black tea polyphenols, which induce apoptosis in human colon cancer cells, cause acute upregulation of RGS10 expression." (PMID 21044322, 2010). "This five-gene signature (RGS11, RGS10, RGS13, RGS4, and RGS3) is overexpressed in ovarian cancer and involved in extracellular matrix–receptor interaction, the TGF-β signaling pathway, the Wnt signaling pathway, and the chemokine signaling pathway." (PMID 39145770, 2024). "RGS10 expression is regulated by DNMT1 and HDAC1, and dysregulation of RGS10 reduces chemoresistance in ovarian cancer cells." (PMID 37649067, 2023). "Our results suggest that HDAC1 and DNMT1 contribute to the suppression of RGS10 during acquired chemoresistance and support growing evidence that inhibition of HDAC1/DNMT1 represent novel therapeutic approaches to overcoming ovarian cancer chemoresistance." (PMID 24475290, 2014). "Our results suggest that HDAC1 and DNMT1 contribute to the suppression of RGS10 during acquired chemoresistance and support inhibition of HDAC1 and DNMT1 as an adjuvant therapeutic approach to overcome ovarian cancer chemoresistance." (PMID 24475290, 2014). "RGS10-1 transcript expression in CAOV-3 ovarian cancer cells is approximately 20% of the expression level seen in IOSE cells, comparable to the fold reduction observed for total RGS10 transcript." (PMID 23533674, 2013).
ovarian carcinoma (continued). "Our results establish RGS10 and RGS17 as novel regulators of cell survival and chemoresistance in ovarian cancer cells and represents the first link between any RGS protein and cancer chemoresistance." (PMID 21044322, 2010). "Establishing this important mechanism involving RGS10 and RGS17 is the first part of a systematic evaluation of cellular signaling in ovarian cancer chemoresistance." (PMID 21044322, 2010). "The current study focuses on the role of RGS10 and RGS17 in determining chemoresistance in ovarian cancer cells." (PMID 21044322, 2010). "This study introduces RGS10 and RGS17 as novel mediators of chemoresistance in ovarian cancer cells." (PMID 21044322, 2010). "In addition to RGS2, other RGS proteins such as RGS5, RGS10 and RGS17 are also closely related to ovarian cancer." (PMID 37649067, 2023). "Further investigation demonstrated the contribution of HDAC1 and DNMT1 to silencing of RGS10 during acquired chemo-resistance and revealed the importance of HDAC1 and DNMT1 inhibition as an assistant therapeutic approach to overcome ovarian cancer chemo-resistance." (PMID 33680048, 2020). "Our study supports RGS10 genes as targets for demethylating and acetylating therapy and identifies RGS10 de-suppression as a likely contributing mechanism for the clinical efficacy of DNMT1 and HDAC1 inhibitors in the treatment of chemoresistant ovarian cancer." (PMID 24475290, 2014). "The high concentration of CpG dinucleotides in the RGS10-1 promoter suggests that the RGS10 gene is a potential target for regulation by DNMT enzymes and may be suppressed in ovarian cancer progression by enhanced DNA methylation." (PMID 23533674, 2013). "Future studies will determine if HDAC inhibition and DNMT inhibition can synergistically increase RGS10-1 expression, and define the role that RGS10 expression may play in the therapeutic effects of HDAC and DNMT inhibitors in ovarian cancer." (PMID 23533674, 2013). "Our results suggest that DNMT and HDAC enzymes may suppress RGS10 expression in ovarian cancer cells, and therefore inhibition of DNMT and HDAC enzymes should enhance RGS10 expression." (PMID 23533674, 2013). "Taken together, these data show that RGS2, RGS10, and RGS17 transcripts are commonly downregulated in acquired chemoresistance in three distinct ovarian cancer cell lines resistant to three distinct chemotherapeutics, while RGS5 was down-regulated in two of the models." (PMID 21044322, 2010). "Our results establish RGS10 and RGS17 as novel regulators of cell survival and chemoresistance in ovarian cancer cells and suggest that their reduced expression may be diagnostic of chemoresistance." (PMID 21044322, 2010). "While total levels of histone H3 are similar at both RGS10 and GAPDH promoters in chemosensitive and chemoresistant cells, levels of acetylated histone H3 are significantly lower at RGS10 promoters in the chemoresistant C13 ovarian cancer cells as compared to chemosensitive OV2008 cells." (PMID 24475290, 2014). "However, the mechanism of suppression of RGS10 expression in ovarian cancer has not been established." (PMID 23533674, 2013). "Our observation that inhibition of RGS10 and RGS17 expression enhances cell survival in the presence of chemotherapeutics suggests that endogenous RGS10 and RGS17 may suppress constitutive survival signals in ovarian cancer cells." (PMID 21044322, 2010). "Finally, we observed that RGS10 and RGS17 are able to suppress LPA-induced activation of the survival factor AKT, suggesting a mechanistic model for RGS10 and RGS17 control of chemoresistance in ovarian cancer cells." (PMID 21044322, 2010).
Parkinson disease (3 papers, 2021 to 2025). A progressive degenerative disorder of the central nervous system characterized by loss of dopamine producing neurons in the substantia nigra and the presence of Lewy bodies in the substantia nigra and locus coeruleus. "In fact, RGS10 was directly connected with IBD in an experiment concerning the overlap between Parkinson’s disease (PD) and IBD." (PMID 38203748, 2024). "Regulator of G-protein signaling 10 (RGS10), a key homeostatic regulator of immune cells, has been implicated in multiple diseases associated with aging and chronic inflammation including Parkinson’s Disease (PD)." (PMID 39994765, 2025).
schizophrenia (3 papers, 2013 to 2019). A major psychotic disorder characterized by abnormalities in the perception or expression of reality. "Also, a novel polymorphism in the RGS domain RGS10 was reported in a Japanese patient with schizophrenia, but the functional significance of RGS10 and its protein expression levels in psychiatric disorders is still unknown." (PMID 24278459, 2013). "Polymorphisms in RGS10 were reported in a cohort of Japanese schizophrenia patients but with negative association data." (PMID 27529621, 2016).